EPOR (erythropoietin receptor)
Diseases named in the same sentence as EPOR in open-access papers (continued):
Sharing a sentence is not in itself a finding about the gene and the disease.
peritonitis (2 papers, 2016 to 2021). Inflammation of the peritoneum (tissue that lines the abdominal wall and covers most of the organs in the abdomen). "Moreover, the administration of rhEPO significantly enhanced levels of macrophage PPARγ and myeloid EPOR deficiency strongly reduced levels of macrophage PPARγ during E. coli-induced peritonitis." (PMID 33927725, 2021). "However, the EPOR level in exudate leucocytes decreased at 6 h, most likely representing a loss of resident macrophages immediately following peritonitis." (PMID 27397585, 2016). "Levels of peritoneal EPO and macrophage erythropoietin receptor (EPOR) were elevated in self-limited E. coli-initiated peritonitis." (PMID 33927725, 2021). "As EPOR was mainly detected in macrophages during the self-limited E. coli peritonitis, we next sought to investigate the role of macrophage EPO signaling in infection resolution." (PMID 33927725, 2021). "Because EPOR was mainly expressed in macrophages during acute peritonitis, we next sought to investigate the role of macrophage EPO signalling in inflammation resolution." (PMID 27397585, 2016). "Our results indicated that EPOR expression increased in an HIF-1α-dependently manner during acute peritonitis." (PMID 27397585, 2016). "In zymA-stimulated peritonitis, while the maximum number of exudate neutrophils in both groups remained comparable, exudate neutrophil infiltration peaked at ∼6 and 12 h in the EPOR-C mice and EPOR-MKO mice, respectively." (PMID 27397585, 2016). "Our results demonstrated that EPO and EPOR expression is induced in zymA-induced peritonitis." (PMID 27397585, 2016). "However, PPARγ upregulation in macrophages was significantly decreased in EPOR-MKO and CGD mice during zymA-induced peritonitis, indicating potential regulation by EPO signalling." (PMID 27397585, 2016). "During acute peritonitis, PPARγ agonist treatment increased macrophage phagocytosis of ANs in EPOR-MKO mice; however, EPO did not enhance this process during acute peritonitis in PPARγ-MKO mice, demonstrating the important contribution of PPARγ to mediating EPO-promoted efferocytosis." (PMID 27397585, 2016).
thalassemia (2 papers, 2013 to 2021). An inherited blood disorder characterized by a decreased synthesis of one of the polypeptide chains that form hemoglobin. "Erythropoietin receptor agonists either alone, or more commonly in combination with hydroxy urea have been shown to have beneficial activity in ß-thalassemia and SCA." (PMID 23157711, 2013). "In thalassemia, erythropoiesis is finely regulated by a complex network of transcription factors, including those involved in erythropoiesis like the erythropoietin receptor EPOR, glycophorin, and Globin peptide chains." (PMID 34650160, 2021). "In this report, murine models of ß-thalassemia and SCA have been characterized and the comparative effects of a novel erythropoietin receptor agonist fusion protein and darbepoetin-α described." (PMID 23157711, 2013).
abdominal aortic aneurysm (1 paper, 2025). Enlargement and ballooning of the vessel that supplies arterial blood to the abdomen, pelvis and legs. "In a recent work, EPO/EPOR signaling was considered to be evidence as an essential mediator of angiotensin-II-induced abdominal aortic aneurysm in Apoe−/− mice." (PMID 40259928, 2025).
acute lymphoblastic leukemia (1 paper, 2025). Leukemia with an acute onset, characterized by the presence of lymphoblasts in the bone marrow and the peripheral blood. "Rearrangements of EPOR are well-known in acute lymphoblastic leukemia, and amplification of EPOR has recently been reported as a recurrent driver event in AEL." (PMID 40162972, 2025).
adrenal hyperplasia (1 paper, 2017). "Examples include the erythropoietin receptor (EPOR), the androgen receptor (AR) [complete androgen insensitivity (CAIS)], and some hormonal excesses and deficiencies (virilizing adrenal hyperplasia and genetic growth hormone deficiency, and likely myostatin deficiency)." (PMID 29075233, 2017).
aplastic anemia (1 paper, 2012). Anemia resulting from bone marrow failure (aplastic or hypoplastic bone marrow). "The veryhighest Epo levels, found for example in aplastic anemia, of 10 U/ml, result in90% EpoR occupancy." (PMID 22969412, 2012).
bone marrow failure syndrome (1 paper, 2024). "Given the frequency of BM failure within the pedigree, we examined known recurrent mutations of inherited bone marrow failure syndromes, such as mutations in genes encoding ribosomal proteins (RP), ALAS2, GATA1, CDAN1, EPO, EPOR, etc.." (PMID 38971858, 2024).
cervical squamous cell carcinoma (1 paper, 2019). A squamous cell carcinoma arising from the cervical epithelium. "Erythropoietin (EPO) and erythropoietin receptor (EPO-R) could produce an angiogenic effect to promote cervical squamous cell carcinoma (CSCC) progression." (PMID 30915348, 2019).
chronic granulomatous disease (1 paper, 2016). Chronic granulomatous disease (CGD) is a rare primary immunodeficiency, mainly affecting phagocytes, which is characterized by an increased susceptibility to severe and recurrent bacterial and fungal infections, along with the development of granulomas. "Macrophage-specific erythropoietin receptor-deficient mice and chronic granulomatous disease (CGD) mice, which lack the capacity for respiratory burst, display impaired inflammation resolution, and exogenous erythropoietin enhances this resolution in WT and CGD mice." (PMID 27397585, 2016).
clear cell carcinoma (1 paper, 2013). "As Caki-1 and SKRC44 cells are each derived from clear cell carcinomas, the high Epo and EpoR expression levels may be either dependent or independent of HIF-1α in clear cell carcinoma cell lines." (PMID 23833638, 2013).
COVID-19 (1 paper, 2022). A disease caused by infection with severe acute respiratory syndrome coronavirus 2. "One finding that may be specific to ESKD is the dynamic temporal profile of the erythropoietin receptor (EPOR) in severe/critical COVID-19 versus a more stable profile in mild/moderate disease." (PMID 36522333, 2022).
E. coli infection (1 paper, 2021). "Following E. coli infection, EPOR was mainly detected on macrophages but not PMNs, in line with our previous observations." (PMID 33927725, 2021).
epilepsy (1 paper, 2018). A brain disorder characterized by episodes of abnormally increased neuronal discharge resulting in transient episodes of sensory or motor neurological dysfunction, or psychic dysfunction. "Results of the study show a specific EpoR expression in cultured primary murine brain cells, frozen brain sections of healthy young mice, and upregulation of EpoR in injured mice brains and patients suffering from epilepsy." (PMID 29393890, 2018).
follicular thyroid cancer (1 paper, 2023). "Of note, ZMAT3 induction by the erytropoietin/erytropoietin receptor (Epo/EpoR) axis was reported in the papillary thyroid cancer subtype but not in others as anaplastic and follicular thyroid cancer." (PMID 37372430, 2023).
glaucoma (1 paper, 2022). Increased pressure in the eyeball due to obstruction of the outflow of aqueous humor. "In this review, we discuss the correlation between glaucoma and EPO, physiology and potential neuroprotective function of the EPO/EPOR system, and latest evidence for the treatment of glaucoma with EPO." (PMID 36555679, 2022). "In this review, we introduce and discuss the neuroprotective function of the EPO/EPOR system and the latest evidence of the treatment of glaucoma with EPO." (PMID 36555679, 2022).
head and neck squamous cell carcinoma (1 paper, 2015). A squamous cell carcinoma that arises from any of the following anatomic sites: lip and oral cavity, nasal cavity, paranasal sinuses, pharynx, larynx, and salivary glands. "There are reports on the relation of EPO and EPOR expression in other cells, such as endothelial cells and head and neck squamous cell carcinoma." (PMID 26376749, 2015).
hemochromatosis (1 paper, 2014). A disorder of iron metabolism characterized by a triad of HEMOSIDEROSIS; LIVER CIRRHOSIS; and DIABETES MELLITUS. "Candidate gene DNA sequencing experiments have identified mutations in the globin loci, but also in the erythropoietin receptor (EPOR) and hemochromatosis (HFE) genes." (PMID 24705286, 2014).
hemorrhage (1 paper, 2023). Loss of blood from the vascular compartment to the exterior or into nonvascular body space as a result of rupture or severance of the blood vessels. "To shed light on this issue, we investigated erythropoietin (Epo), erythropoietin receptor (EpoR), and Y-box binding protein 1 (YB-1) concentrations in the fracture zone in a porcine MT + traumatic hemorrhage (TH) model." (PMID 36639666, 2023).
left ventricular hypertrophy (1 paper, 2022). Enlargement of the LEFT VENTRICLE of the heart. "Anti-EPOR antibody positivity was associated with left ventricular hypertrophy and systolic dysfunction in patients with CKD on HD." (PMID 36140193, 2022).
Lewis lung carcinoma (1 paper, 2005). "In this study, we examined the effect of darbepoetin alfa on chemotherapy sensitivity and delivery in an in vivo model of Lewis lung carcinoma, shown here to express the Epo receptor (EpoR)." (PMID 15999100, 2005).
liver cancer (1 paper, 2025). An epithelial or non-epithelial malignant neoplasm that arises from the liver. "This study uncovers a potential molecular mechanism by which FODMAP‐related dietary patterns may modulate liver cancer risk through the TGFB3/EPOR/ELANE/C3 signaling axis." (PMID 40895144, 2025). "Mediation MR indicated that cheese intake influenced liver cancer risk indirectly by modulating TGFB3, EPOR, ELANE, and C3 expression, accounting for 8.8%, 25%, 1.8%, and 12.7% of the total effect, respectively." (PMID 40895144, 2025). "MR findings suggest that higher cheese intake is associated with reduced liver cancer risk, with partial mediation through modulation of TGFB3, EPOR, ELANE, and C3 expression." (PMID 40895144, 2025). "The present mechanistic analyses highlight EPOR as a potential key mediator connecting FODMAP dietary components with liver cancer development." (PMID 40895144, 2025). "Using a two‐step MR framework, we evaluated whether TGFB3, EPOR, ELANE, and C3 mediate the causal association between FODMAP dietary intake and liver cancer risk." (PMID 40895144, 2025). "Protein‐level analyses identified four trogocytosis‐ and efferocytosis‐related proteins, TGFB3, EPOR, ELANE, and C3, that may mediate these dietary effects on liver cancer susceptibility." (PMID 40895144, 2025). "The MR results revealed significant associations between three FODMAP dietary components, cheese, cereal, and dried fruit intake, and six liver cancer‐related proteins (ANXA2, SFTPD, TGFB3, EPOR, ELANE, and C3)." (PMID 40895144, 2025). "Furthermore, these findings emphasize the pivotal roles of TGFB3, EPOR, and ELANE in liver cancer, especially regarding dietary factors such as cheese intake." (PMID 40895144, 2025).
lupus nephritis (1 paper, 2022). Glomerulonephritis in the context of systemic lupus erythematosus. "The proportion of patients positive for anti-EPOR antibodies in this study was 4.5%, which is smaller than found in patients with CKD in previous studies that included some causes of CKD with lupus nephritis, DM, ANCA vasculitis, and maintenance HD." (PMID 36140193, 2022).
mastitis (1 paper, 2020). Inflammation of breast tissue during lactation or postpartum due to an obstructed duct or infection. "Five genes (EPOR, IL9, IFNL3, CCL26, and IL26) that were involved in this pathway might serve as potential molecular markers for breeding programs that enhance resistance to S. aureus infection and mastitis." (PMID 32944235, 2020).
metastatic cancers (1 paper, 2013). A carcinoma which has spread from the original site of growth to another anatomic site. "EPO and EPOR levels were only slightly increased in metastatic cancers without reaching significance (data not shown)." (PMID 24165569, 2013).
myocardial hypertrophy (1 paper, 2022). "The inflammatory milieu has been reported to cause the downregulation of EPOR, hyporesponsiveness of ESA, and increase in fibroblast growth factor 23, which induced myocardial hypertrophy and diastolic dysfunction." (PMID 36140193, 2022).
ocular hypertension (1 paper, 2022). Abnormally high intraocular pressure. "Two weeks after ocular hypertension, the levels of EPO protein and EPOR significantly increased by 1.5 and 3 times compared to normal retina, respectively." (PMID 36555679, 2022).
oesophageal cancer (1 paper, 2007). "Erythropoietin receptor, however, was expressed more abundantly and staining increased from normal squamous tissue to invasive oesophageal cancer." (PMID 17437013, 2007).
of the CNS (1 paper, 2017). "EPOR is expressed in OLs in physiologic conditions, and its levels are increased by hypoxia, injury, and chronic disease, suggesting the involvement of the EPO–EPOR pathway in remyelination upon injury and disease of the CNS." (PMID 29123527, 2017).
oral squamous cell carcinoma (1 paper, 2012). "The present study aimed to evaluate the clinicopathological significance of erythropoietin receptor (EPOR) expression in oral squamous cell carcinoma (OSCC)." (PMID 22639817, 2012).
ovarian adenocarcinoma (1 paper, 2019). An adenocarcinoma that arises from the ovary. "We also demonstrated the existence of two EPOR splice variants in human ovarian adenocarcinoma cell line - A2780 and confirmed the expression of EPOR protein in these cells using specific A82 anti-EPOR antibody." (PMID 30606107, 2019). "We also observed the existence of two EPOR splice variants in human ovarian adenocarcinoma cell line - A2780 and confirmed the expression of EPOR protein in these cells using specific A82 anti-EPOR antibody." (PMID 30606107, 2019). "Moreover, A82 antibody confirmed our previous results demonstrating the presence of functional EPOR in human ovarian adenocarcinoma A2780 cells." (PMID 30606107, 2019).
paraganglioma (1 paper, 2022). A benign or malignant neoplasm arising from paraganglia located along the sympathetic or parasympathetic nerves. "In addition, the correlation coefficient r between EPOR expression and tumor purity exceeded 0.3 in pheochromocytoma and paraganglioma (PCPG)." (PMID 35359375, 2022).
periodontal disease (1 paper, 2024). "Thus, considering our preclinical results, epigenetic activation of EPOR signaling may provide a new strategy to compensate for autologous PDLSC-based strategies for periodontal disease." (PMID 38509204, 2024). "Here, we demonstrated that the silencing of functional EPOR in healthy PDLSCs damaged microenvironment-modulating functions, including stemness, multipotency, and immunomodulatory function, mimicking the characteristics of periodontal disease-specific and ROS-damaged pathological PDLSCs." (PMID 38509204, 2024).
periodontitis (1 paper, 2024). An acute or chronic inflammatory process that affects the tissues that surround and support the teeth. "The EPOR-mediated paracrine function of PDLSCs maintains periodontal immune suppression and bone metabolic balance via osteoclasts and osteoblasts in the periodontitis model mice." (PMID 38509204, 2024). "Furthermore, a PDLSC transplant assay revealed that the EPOR pathway regulates the therapeutic efficacy of PDLSCs in periodontal tissue destruction and inflammation in a ligature-induced periodontitis model." (PMID 38509204, 2024). "To evaluate our hypothesis, we investigated the mimicking of EPOR-knockdown control PDLSCs to periodontitis patient-derived PDLSCs (PD-PDLSCs) and the successful rejuvenation of the dysfunction of PD-PDLSCs via EPO-EPOR signaling." (PMID 38509204, 2024).
pituitary adenomas (1 paper, 2012). "Since the EPO-EPOR signaling has never been investigated in human pituitary adenomas, we first assessed the EPOR expression in 31 human pituitary adenoma samples using immunohistochemistry and Western blotting." (PMID 22086127, 2012). "In the present study, we first characterized EPOR expression in different hormone secreting types of human pituitary adenomas and found no EPOR protein expression in pituitary adenomas." (PMID 22086127, 2012). "In the present study, a two-week rhEPO administration resulted in accelerated tumor growth of MMQ cell xenografts, suggesting that rhEPO administration can accelerate the tumor growth of EPOR negative pituitary adenomas." (PMID 22086127, 2012). "Our results indicate that, at least in our cases, pituitary adenomas are EPOR-negative tumors and rhEPO administration accelerates the growth of pituitary adenomas by promoting tumor angiogenesis via the EPO-JAK2-STAT3-VEGF signaling pathway." (PMID 22086127, 2012). "In this study, for the first time, we present the evidence that pituitary adenomas are EPOR-negative tumors." (PMID 22086127, 2012). "In this study, we found no EPOR protein expression in pituitary adenoma samples." (PMID 22086127, 2012). "In the present study, we demonstrated that, at least in our cases, pituitary adenomas are EPOR negative tumors and systematic rhEPO administration may promote tumor growth of pituitary adenomans via enhancing angiogenesis though the EPO-JAK2-STAT3-VEGF signal pathway." (PMID 22086127, 2012). "Here we demonstrated for the first time that human pituitary adenomas are EPOR negative tumors and rhEPO accelerated the tumor growth of MMQ pituitary adenoma xenografts via enhancement of angiogenesis in vivo, whereas rhEPO displayed no direct effect on MMQ cells in vitro." (PMID 22086127, 2012).
proliferative diabetic retinopathy (1 paper, 2009). Advanced retinopathy due to diabetes mellitus characterized by the formation of new vessels in the retina. "One report detected EPOR in human epiretinal membrane of proliferative diabetic retinopathy." (PMID 19930719, 2009).
pulmonary hypertension (1 paper, 2014). Increased pressure within the pulmonary circulation due to lung or heart disorder. "However, mice with EpoR restricted to erythroid tissue do not show gross morphologic defects in the cardiovascular system, although they are more susceptible to pulmonary hypertension and pulmonary vascular remodeling." (PMID 24918289, 2014).
Renal cyst (1 paper, 2013). A fluid filled sac in the kidney. "In conjunction with von Hippel-Lindau (VHL) gene deficiency, the co-expression of Epo and EpoR in renal cysts and tumors may reflect developmental arrest in immature mesenchymal cells." (PMID 23833638, 2013). "The co-expression of Epo and EpoR has been detected in numerous renal cysts, providing further evidence that renal cysts are potential precursors to RCC." (PMID 23833638, 2013). "Therefore, the co-expression of Epo with EpoR in VHL-associated RCC and renal cysts suggests that a precursor cell of renal lesions is a developmentally arrested, pluripotent embryonic cell derived from nephrogenous mesenchyme." (PMID 23833638, 2013).
sarcoma (1 paper, 2022). A usually aggressive malignant neoplasm of the soft tissue or bone. "The analysis showed that EPOR expression was positively correlated with the TMB of COAD (p = 2.5e - 05), sarcoma (SARC) (p = 0.012), and SKCM (p = 0.0067) and negatively correlated with the TMB of BRCA (p = 3.6e - 13), CESC (p = 0.03), KIRP (p = 0.01), LIHC (p = 0.0006), and PAAD (p = 0.019)." (PMID 35359375, 2022).
skin tumor (1 paper, 2013). "In this experiment, an EpoR band was readily detected by A82 in positive control erythroid progenitor lysates and not in negative control 769-P lysates and no EpoR was detected in any of the normal skin samples or skin tumor cell lines." (PMID 23861852, 2013).
tongue cancer (1 paper, 2012). A malignant neoplasm affecting the tongue. "High EPOR expression in tumor tissue was found to be significantly correlated with high microvascular density in tongue cancer in an immunohistochemical study." (PMID 22639817, 2012).